CD4 (CD4 molecule)
Diseases named in the same sentence as CD4 in open-access papers (continued):
Sharing a sentence is not in itself a finding about the gene and the disease.
COVID-19 (continued). "One study found evidence of significant decreases in counts of CD3+ T, CD4+ T, CD8+ T, and NK cells in COVID-19 patients compared with healthy controls (all p<0.05) on admission." (PMID 33493185, 2021). "Translational studies in adult COVID-19 identified T cell lymphopenia in particular, with a preferential decrease in CD8+ T cells compared to CD4+ T cells." (PMID 33653907, 2021). "Analyzing the different lymphocyte subpopulations, we have shown lower than normal levels of helper T (Th) cells (CD3+CD4+) in both of the studied groups of patients, with significantly reduced Th lymphocyte levels in the ICU COVID-19 patients (p = 0.002)." (PMID 34071149, 2021). "In summary, we measured the dynamics of SARS-CoV-2-specific antibodies and CD4+ and CD8+ T cell responses in COVID-19 patients." (PMID 33563974, 2021). "Specifically, total lymphocytes, B cells, CD4+ T cells, CD8+ T cells, and NK cells were decreased in COVID-19 patients, and severe patients were more severe than mild patients." (PMID 33987176, 2021). "CD4+ and CD8+ T cells in acute COVID-19 patients showed a substantial reduction of CXCR3 and CXCR5 expression, irrespective of disease severity, that is recovered upon convalescence." (PMID 34595175, 2021). "There were insufficient data on the effect of CD4+ T-cell count and HIV viral load on COVID-19 outcomes." (PMID 33587448, 2021). "For most pediatric patients, the frequency of PD-1+ CD4+ T cells was similar to adults; however, PD-1+ CD4+ and CD8+ T cell frequencies were substantially higher in MIS-C compared to pediatric COVID-19." (PMID 33653907, 2021). "In COVID-19 patients, more effector phenotype was found in CD8+ T cells, while CD4+ T cells had more central phenotype." (PMID 34945761, 2021). "The relative MFIs of CD69 and CD44 in CD4+ T cells, CD8+ T cells, and NK cells were significantly lower in RTP patients than in patients with moderate COVID-19 and severe COVID-19." (PMID 34687295, 2021). "Expression of HLA-DR and CCR5 in acute COVID-19 monocytes positively correlated with CD4 and CD8 T cell proliferation, reaching significance in the case of CD4 T lymphocytes." (PMID 34572439, 2021). "The developed assay of stimulating human PBMC specimens with live SARS-CoV-2 can successfully detect virus-specific populations of CD4+ and CD8+ memory T cells in patients who have recovered from COVID-19." (PMID 34452355, 2021). "Initially, we observed that SARS-CoV-2-specific memory CD4+ and CD8+ secreted low levels of IFNγ and only a small proportion of the T cells from COVID-19 patients gained multifunctionality (IFNγ and TNF dual expression)." (PMID 33741972, 2021). "Metabolic changes in other subsets of CD4+ and CD8+ T cells were also observed in COVID-19 patients." (PMID 33936072, 2021). "Regarding the age-specific effects of COVID-19, in this study, older patients had lower lymphocyte and CD8+ T cell counts, resulting in a higher CD4+/CD8+ T cell ratio in both sexes." (PMID 33770147, 2021). "Two injections of 1–50 μg of BNT162b1 induced intense antibody production, with RBD-binding IgG titers and CD4+ and CD8+ T-cell responses far exceeding those observed in the sera of individuals who recovered from COVID-19." (PMID 34205434, 2021). "We observed a significant decline of naïve CD4+ and CD8+ T cells in patients with both mild and severe COVID-19." (PMID 33546489, 2021). "Severe COVID-19 patients experience hyperactivation of immune responses, predominantly polyfunctionality in CD8+ T cells, distinct CD4+ T-cell subpopulations, and B-cell heterogeneity." (PMID 34899693, 2021). "Moreover, as mentioned in Section 3, marked lymphopenia is associated with severe cases of COVID-19, and it was found that the proliferation of non-naïve CD4+ and non-naïve CD8+ T cells was significantly higher in COVID-19 patients than in healthy donors or recovered donors." (PMID 33923792, 2021).
COVID-19 (continued). "In order to explore the impact of a COVID-19 vaccine on ART efficacy in PLWH, we compared the CD4+ T cell counts and VL 6 months ago versus the results during this visit." (PMID 34960204, 2021). "In COVID-19 patients, the perivascular space around the damaged endothelium is infiltrated by increased numbers of CD3+ and CD4+ T-lymphocytesand the process of angiogenesis is skewed towards an intussusceptive pattern of vessel formation." (PMID 34512643, 2021). "Development of adaptive immunity after COVID-19 and after vaccination against SARS-CoV-2 is predicated on recognition of viral peptides, presented on HLA class II molecules, by CD4+ T-cells." (PMID 34349756, 2021). "T-cell lymphopenia, particularly the CD4+ T-lymphocyte subset, and an increased neutrophil to lymphocyte ratio (NLR) (indicator of inflammation) has also been observed in COVID-19 patients and correlates with disease severity." (PMID 35046961, 2021). "In some patients, memory CD4+ and CD8+ T cells have generated responses for numerous COVID-19 proteins, such as the nucleoprotein and spike proteins." (PMID 34681059, 2021). "The authors reported that total lymphocytes, CD4+ T cells, CD8+ T cells, B cells, and natural killer (NK) cells were decreased among patients with COVID-19, more so in severe cases than in mild cases." (PMID 34185801, 2021). "These cell types were often the most profoundly and persistently affected by severe COVID-19 (particularly MAIT, gd T, Tfh, and CD4+ Temra cells)." (PMID 34051148, 2021). "SARS-CoV-2-specific CD4+ effector cells generally do not express Th2 traits, which could play a protective role as shown by the lower susceptibility and less severe outcomes of COVID-19 in asthmatic and atopic patients." (PMID 35140709, 2021). "Further, as lymphocyte counts are considered reliable predictors of disease severity and mortality in COVID-19 patients, it is critical for SARS-CoV-2 infected patients to overcome lymphocyte suppression, especially with regard to their CD4 T cell counts." (PMID 34251989, 2021). "CD4+ and CD8+ T cell counts were significantly reduced in severe COVID-19 patients compared with the two OTD subject groups." (PMID 34858405, 2021). "Overall, these results demonstrate that naïve CD4+, CD8+, Treg, and B cell pools, as well as CD56bright NK cells, which are all depleted in severe COVID-19, also decrease with age." (PMID 34434199, 2021). "When we analyzed the GMF intensity of CD25+ on CD4+ and CD8+ cells we also observed the lowest proportion in patients with COVID-19(+)." (PMID 33419040, 2021). "In patients with severe COVID-19, the levels of Hs-CRP, PCT, and D-dimer were elevated, whereas the levels of lymphocytes, CD4+T cell, and CD8+T cell were decreased." (PMID 33435865, 2021). "We revealed that most of the COVID-19 patients had lower than normal levels of CD3+ T cells, CD4+ T cells, CD8+ T cells, B cells and NK cells." (PMID 34123873, 2021). "Studies have identified that there are both CD4 and CD8 T-cell responses in patients who had recovered from COVID-19 and in individuals who had received an investigational SARS-CoV-2 vaccine." (PMID 34284812, 2021). "CD4+ and CD8+ lymphopenia is commonly found in COVID-19 patients, resulting possibly either from direct cytotoxic effects of the virus, or from enhanced T-cell apoptosis due to the dysregulated cytokine milieu or metabolic disorders such as lactic acidemia." (PMID 34512643, 2021). "Among convalescent COVID-19 patients, for TRA, the most frequently used gene segments were TRAV12-3 and TRAJ42 in either CD4+ T or CD8+ T cells, while the frequencies of TRBV23-1 and TRBJ2-7 were significantly higher for TRB." (PMID 35011632, 2021). "Our findings showed that spike viral protein led to the activation of CD8+ T and CD4+ T helper cells producing IFN-γ (Th1), and expression of genes related to interferon pathways in COVID-19 individuals." (PMID 34571855, 2021).
COVID-19 (continued). "Most of T cell reactivity to the viral Spike protein was dependent on CD4+ T cells and these responses were correlated with anti-SARS-Cov-2 IgG and IgA titres in COVID-19 cases." (PMID 34595175, 2021). "Beyond humoral immunity, broad and strong memory CD4+ and CD8+ T cells are detected in convalescent COVID-19 patients." (PMID 34696190, 2021). "Lymphocytopenia and decreased CD3, CD4, and CD8 counts were common in patients with COVID-19 and correlate with disease severity." (PMID 34946272, 2021). "Recent studies have highlighted that the concentration of CXCL10 negatively correlates with the width of the CD4 + and CD8 + T cell repertoire in patients with acute COVID-19." (PMID 34663207, 2021). "In our cohort, CD3 + CD4 − CD8 − DN T-lymphocyte absolute counts were significantly reduced in nonsurvivors and progressively decreased from mild to severe COVID-19 patients." (PMID 34140530, 2021). "As the expression of TREM-2 on CD4+ T cells of patients significantly increased, we then focused on the role of TREM-2–expressing CD4+ T cells in COVID-19 in the following experiments." (PMID 34878838, 2021). "In COVID-19 patients, the strongest immune system responses to SARs-CoV-2 infection was directly related to the detected level of T-cell (mainly CD8 + and CD4 + ) due to their responses to the SARs-CoV-2 spike protein (S)." (PMID 33519271, 2021). "A significant increase in GM-CSF+ CD4 T cells with extremely high ex vivo IL-6 and IFN-γ production was reported in critically ill COVID-19 patients." (PMID 34603758, 2021). "The CD4+ TH1-lineage was similarly characterized by increased IFN- (type I and II) and interleukin (IL6, IL12, IL21) signaling in mild COVID-19." (PMID 33473155, 2021). "Overall, the data show that CD4+ and CD8+ T cell memory are generated by both low-dose and 100-μg dose COVID-19 mRNA-1273 vaccine." (PMID 34519540, 2021). "There are also inconsistent reports of anti-viral CD4+ T-cell, CD8+ T-cell responses, and humoral immune responses in patients with different COVID-19 severity." (PMID 35095917, 2021). "We observed that the proliferative capacity of polyclonal CD4 T cells was similar in clusters A and B, while that of CD8 T cells was higher in the COVID-19 patients from cluster B." (PMID 34572439, 2021). "Several studies have reported a state of lymphopenia in CD4+ T, CD8+ T, B and NK cells in COVID-19 patients, however others have shown higher reductions of CD8+ T than that CD4+ T cells." (PMID 35126355, 2021). "Increasing experimental evidence suggests the development of CD4+ and CD8+ T-cell responses in a majority of patients who recovered from COVID-19; however, their role in disease progression and protection is not well understood." (PMID 34780495, 2021). "Spike protein from SARS-CoV-2 showed to be a good T-cell stimulation for COVID-19, with high production of IFN-γ, IL-2, and TNF by CD4+ T cells, characterizing the predominant response of Th1 cells." (PMID 34571855, 2021). "This review documents studies that found decreased T-lymphocytes subsets mainly CD4+ T and CD8+ T cells as well as elevated cytokines such as IL-6 in severe and critically ill COVID-19 patients." (PMID 34287285, 2021). "Altogether, the antigen-specific T cell analyses suggest predominant and widespread CD4+ T cells responses over the CD8+ T cells in both the unexposed and recovered mild COVID-19 patients." (PMID 33777028, 2021). "viSNE analysis of the overall CD3+ T cells and CD4+ and CD8+ T cell subsets showed a decreasing population size in patients with moderate and severe COVID-19 as well as in comorbidity control patients compared with healthy donors." (PMID 33986193, 2021). "Frequencies of activated (HLA-DR+CD38+ or Ki67+) CD8+ and CD4+ T cells and activated CX3CR1+ CD8+ T cells remained elevated in MIS-C even when compared to the severe subgroup of pediatric COVID-19." (PMID 33653907, 2021).
COVID-19 (continued). "Coordinated SARS-CoV-2 adaptive immune response of two arms, including neutralizing antibody and T cell, were associated with milder disease, highlighting the importance of both CD4+ and CD8+ T cells in protective immunity in COVID-19." (PMID 34696201, 2021). "By contrast, in non–COVID-19 controls, the memory profile of SARS-CoV-2–reactive CD4+ T cells was highly variable between individuals, with 50% exhibiting predominantly a late differentiation profile (CD45RA–CD27–)." (PMID 33945513, 2021). "This prompted us to assess the phenotypic and functional status of NK cells in particular, as well as monocytes and CD4 and CD8 T cells, in patients presenting with clinically moderate to severe interstitial pneumonia emerging in the setting of COVID-19." (PMID 33060840, 2021). "By first restoring and then maintaining adequate peripheral blood levels of CD4+ and CD8+ T lymphocytes this would enable the immune system of an SCC-treated COVID-19 patient to respond appropriately to resolve SARS-CoV-2 infection." (PMID 33777973, 2021). "First, we compared the prevalence, magnitude, and phenotypical profile of SARS-CoV-2–responding CD4+ T cells (e.g., cells producing IFN-γ, TNF-α, or IL-2) between hospitalized non–COVID-19 controls and confirmed COVID-19 patients." (PMID 33945513, 2021). "Polyfunctional CD4+ and CD8+ T cell responses are elicited against the SARS-CoV-2 spike protein after two doses of the AZD1222 COVID-19 vaccine." (PMID 34591596, 2021). "Single cells-based CytTOF analysis, performed in our small group of patients, confirms the reduction in the CD8+ and in the CD4+ T lymphocyte subpopulations, observed by FCA in COVID-19 patients with low FT3." (PMID 33794925, 2021). "On CD3+CD4+CD45RO+ memory T cells, we observed a clear reduction of α4β7 expression in patients with active COVID-19." (PMID 33959123, 2021). "Prominently, the antigen-specific CD4+ and CD8+ T cells are specifically observed during day 0 to day 28 in COVID-19-vaccinated individuals." (PMID 35250966, 2021). "While cell numbers were higher in blood, higher frequencies of intermediate (CD14+CD16+) monocytes/macrophages, activated (HLADR+CD38+) and EM-like (CD27−CD45RA−) CD4+ and CD8+ T-cells were found in COVID-19 respiratory specimens compared to blood." (PMID 34462740, 2021). "In the Asia-Pacific region, Singapore used to recommend COVID-19 vaccination to PLWHA who are receiving antiretroviral therapy (ART), with suppressed HIV viral load, and with CD4+ T cell counts over 200 cells/μL." (PMID 34543223, 2021). "In contrast to this, CD4+ T cells and, in particular, those displaying a TH17 polarization state mainly expanded in the BALF of patients with COVID-19." (PMID 33622974, 2021). "Previously, both helper T cells (CD3+CD4+) and cytotoxic T cells (CD3+CD8+) in patients with COVID-19 were found to be below normal levels, and this decline in helper T cells was more pronounced in severe cases." (PMID 34696395, 2021). "Ongoing research has shown that lymphocytes and the subsets of CD4+ T cells, CD8+ T cells, B cells, and natural killer (NK) cells also play an important role in the maintenance of immune system function during COVID-19." (PMID 34571981, 2021). "The number of total T cells and CD4+ and CD8+ T cells was dramatically reduced in COVID-19 patients, especially, which was strongly correlated with patient deterioration." (PMID 34238338, 2021). "Specifically, CD4+T lymphocytes, CD8+T lymphocytes, and NKT lymphocytes were all reduced in all critically ill patients, indicating that COVID-19 leads to impairment of lymphocytes in the immune system." (PMID 33735325, 2021). "The quantity of neutralizing antibodies and total SARS-CoV-2-specific CD4 and CD8 T cells correlates in convalescent mild COVID-19 patients." (PMID 38626271, 2021).
COVID-19 (continued). "In the case of COVID-19, although SARS-CoV-2 is a novel pathogen, it shares extensive CD4+ and CD8+ T-cell cross reactivity with human endemic coronaviruses and would therefore elicit a secondary T-cell response to the cross-reactive epitopes." (PMID 34650566, 2021). "Of the 10 COVID-19 patients available for analysis, 5 individuals had at least one hotspot of great change, as revealed by T-REX, in CD4+ T cell-specific analysis." (PMID 34350827, 2021). "The main lymphocyte subpopulations (CD3+CD4+, CD16+CD56+, and CD4+/CD8+ ratio) and cytokines (TNF-α and IFN-γ) of COVID-19 patients were significantly different from that of CAP patients." (PMID 34150910, 2021). "It has been found that the total number of circulating lymphocytes, CD4 + T cells, CD8 + T cells and B lymphocytes are decreased in patients with ARDS or death of COVID-19." (PMID 34074305, 2021). "It has been shown that in patients with severe COVID-19 treatment with leronlimab reduces elevated plasma IL-6 and chemokine ligand 5 (CCL5), and normalized CD4/CD8 ratios." (PMID 33521616, 2021). "Previous studies have similarly reported a decline in CD4 and CD8 cells in acute moderate or severe COVID-19 cases, which improved during the resolution period." (PMID 33808906, 2021). "In COVID-19 patients, SARS-CoV-2–specific CD4+ T cells almost exclusively displayed an early differentiated memory phenotype (CD45RA–CD27+, median: 95.1%, IQR: 88.7%–97.4%)." (PMID 33945513, 2021). "Although lymphopenia preferentially affects CD8+ T cells, both CD4+ and CD8+ T cell levels were reduced in number and frequency but exhibited increased activation in COVID-19 patients." (PMID 34198973, 2021). "A recent paper was therefore aimed to evaluate the CD4+ and CD8+ T-cells responses in COVID-19 cases." (PMID 33918624, 2021). "Detection of memory CD4+ and CD8+ T cells primed against SARS-CoV-2 S, N, and M proteins of recovered COVID-19 patients has also been reported." (PMID 34069575, 2021). "AIM T cell responses in COVID-19 vaccinees displayed a memory phenotype irrespective of the variant analyzed, with preferential enrichment for central memory (Tcm) and effector memory (Tem) for CD4+ and Tem and terminally differentiated effector memory (Temra) for CD8+ T cells." (PMID 34949742, 2021). "Histologic evidence of lung endothelial barrier degradation is concomitant to an intense CD4+ and CD8+ T cell infiltrate, suggesting a role of immune-mediated injury in the pathophysiology of severe COVID-19." (PMID 34361874, 2021). "In the COVID-19(−) virus group there was a high positive correlation between the percentage of RE-LYMP and proportion of CD4+ CD38+ cells (R = 0.7, p < 0.05) and between the percentage of RE-LYMP and GMF CD4+ CD38+ intensity (R = 0.8, p < 0.05)." (PMID 33419040, 2021). "In the COVID-19(+) we noticed a lower median proportion of CD4+ CD38+ cells than in the HC group and COVID-19(−) virus group (significant differences between COVID-19(+) and COVID-19(−) virus group, (respectively 11.0% vs. 23.0%, p < 0.05)." (PMID 33419040, 2021). "The proportion of CD4 responders to SARS-CoV-2 and M. tuberculosis were comparable in HIV-uninfected COVID-19 patients (~90%)." (PMID 33945513, 2021). "The number of CD3 lymphocytes and major subsets of CD4 and CD8 T cells were significantly decreased in COVID-19 compared to control subjects, indicating enhanced systemic immunosuppression." (PMID 34789851, 2021). "The severely ill and deceased COVID-19 subjects show expressively lower lymphocyte (CD8+ and CD4+ T cells) levels than the survivors; however, with the higher neutrophil counts compared to lymphocytes." (PMID 33632295, 2021). "We have also analyzed the DN T cells, and in a similar way to what happens with CD4 and CD8 T cells, the activated (HLA-DR+CD38+) and perforin expressing DN T cells are significantly expanded in COVID-19 patients." (PMID 33777054, 2021).